HYMAI (hydatidiform mole associated and imprinted)
Synonyms: NCRNA00020
Gene: Long non-coding RNA gene on chromosome 6 (144,004,916 to 144,008,262, reverse strand). Ensembl gene ENSG00000283122.
Diseases named in the same sentence as HYMAI in open-access papers:
HYMAI is named in the same sentence as 16 diseases in open-access papers, as found by Europe PMC text mining. Sharing a sentence is not in itself a finding about the gene and the disease. The quoted sentences say what the papers report.
diabetes (4 papers, 2018 to 2025). "Even though HYMAI has been found over-expressed in transient neonatal diabetes mellitus patients, the function of this transcript is still unclear." (PMID 40084057, 2025). "The use of MS-MLPA is essential for the diagnosis of 6q24-TNDM, identifying paternal UPD6, paternal 6q24 duplications, or isolated maternal hypomethylation of the PLAGL1/HYMAI locus in patients with diabetes diagnosed in the first weeks of life and other coexisting disorders." (PMID 41153775, 2025). "This included for example the well-known lncRNA MALAT1 and the lncRNA HYMAI, which has been studied in relation to diabetes but not previously reported in association with atherosclerosis or hypoxia." (PMID 30456215, 2018).
transient neonatal diabetes mellitus (3 papers, 2016 to 2025). Transient neonatal diabetes mellitus (TNDM) is a genetically heterogeneous form of neonatal diabetes (NDM) characterized by hyperglycemia presenting in the neonatal period that remits during infancy but recurs in later life in most patients. "A study showed that the abnormal expression of hydatidiform mole associated and imprinted (HYMAI), a special LncRNA that was expressed in paternal alleles, is closely associated with transient neonatal diabetes mellitus (TNDM), and such TNDM co-occurs with defective DNA methylation." (PMID 29050364, 2017). "Transient neonatal diabetes mellitus 1 is caused by overexpression of the maternally imprinted genes PLAGL1 and HYMAI on chromosome 6q24." (PMID 27075368, 2016). "Transient neonatal diabetes mellitus 1 (TNDM1) is an imprinting disorder caused by overexpression of the maternally imprinted genes PLAGL1 and HYMAI on chromosome 6q24." (PMID 27075368, 2016).
hydatidiform mole (2 papers, 2015 to 2023). A gestational trophoblastic disorder characterized by marked enlargement of the chorionic villi, hyperplasia of the villous trophoblastic cells and hydropic changes. "Two imprinted genes, ZAC(zinc finger protein associated with apoptosis and cell cycle arrest) and HYMAI (imprinted in hydatidiform mole) have been identified as potential candidates." (PMID 26631065, 2015). "Finally, HYMAI (hydatidiform mole associated and imprinted) plays an important role in DNA alkylation and methylation." (PMID 37958675, 2023).
acute myeloid leukemia (1 paper, 2025). Acute myeloid leukemia (AML) is a group of neoplasms arising from precursor cells committed to the myeloid cell-line differentiation. "A recent study expounded that HYMAI as an autophagy-related lncRNA may play a complex function and could be considered a favorable prognostic factor in acute myeloid leukemia progression." (PMID 40084057, 2025).
breast carcinoma (1 paper, 2017). "Compared with breast adjacent tissues, AFAP1-AS1, PVT1, HYMAI were downregulated in most breast cancer tissues, and lncRNA PVT1, BANCR, HCG18 were upregulated in lung cancer." (PMID 28938549, 2017). "The results showed that lncRNAs AFAPA-AS1, aHIF, BDNF-AS, HYMAI, UCA1, kucg 1, MALAT1 were differentially expressed in breast cancer tissues (fold change > 2)." (PMID 28938549, 2017). "AHIF, MALAT1, SNHG6, UCA1 expression levels increased in breast cancer tissues compared with their counterpart adjacent tissues, while AFAP1-AS1, PVT1, HYMAI had lower expression in tumors." (PMID 28938549, 2017).
clear cell renal cell carcinoma (1 paper, 2025). "In clear cell renal cell carcinoma patients, HYMAI expression has also been found to be associated with overall survival." (PMID 40084057, 2025).
human papillomavirus infections (1 paper, 2025). "More than that, there is also a close link between altered methylation levels at PLAGL1/HYMAI differentially methylated regions and high-risk human papillomavirus infections." (PMID 40084057, 2025).
Hyperglycemia (1 paper, 2017). An increased concentration of glucose in the blood. "This LOH fragment included PLAG1 and HYMAI genes, which were associated with imprinting disorder intrauterine growth retardation and neonatal hyperglycemia." (PMID 28472932, 2017).
macroglossia (1 paper, 2022). The presence of an excessively large tongue, which may be congenital or may develop as a result of a tumor or edema due to obstruction of lymphatic vessels, or it may occur in association with hyperpituitarism or acromegaly. "Further, chromosome 6q24 has gene imprinting regions, including PLAG1 and HYMAI genes, and abnormalities in these may lead to fetal intrauterine growth retardation, temporary neonatal diabetes, macroglossia, or umbilical hernia." (PMID 35397568, 2022).
neonatal diabetes mellitus (1 paper, 2025). Neonatal diabetes mellitus presents as hyperglycemia, failure to thrive and, in some cases, dehydration and ketoacidosis which may be severe with coma, in a child within the first months of life. "Another study pointed out that imprinted expression of HYMAI in skin fibroblasts is tight in healthy individuals but not in transient neonatal diabetes mellitus patients." (PMID 40084057, 2025).
tumor (2 papers, 2021). "We also identified five lncRNAs with abundant expression (LRRC75A-AS1, HYMAI, NEAT1, XIST and FTX) were closely associated with tumor progression, which may suggest to be the biomarker for the malignancy of GIST." (PMID 34557343, 2021). "Several lncRNAs with abundant expression (LRRC75A-AS1, HYMAI, NEAT1, XIST and FTX) were closely associated with tumor size, which may suggest to be biomarkers for the GIST malignancy." (PMID 34557343, 2021). "The expression of HYMAI, NEAT1, XIST and FTX were negatively correlated with tumor diameter and significantly down-regulated during GIST progression." (PMID 34557343, 2021).
HYMAI also shares sentences with these, for which no sentence is quoted: atherosclerosis (1 paper); cervical cancer (1); lung carcinoma (1); major depressive disorder (1); Umbilical hernia (1).